GART (phosphoribosylglycinamide formyltransferase, phosphoribosylglycinamide synthetase, phosphoribosylaminoimidazole synthetase)
Diseases named in the same sentence as GART in open-access papers:
GART is named in the same sentence as 37 diseases in open-access papers, as found by Europe PMC text mining. Sharing a sentence is not in itself a finding about the gene and the disease. The quoted sentences say what the papers report.
colorectal cancer (5 papers, 2023 to 2025). A primary or metastatic malignant neoplasm that affects the colon or rectum. "As a key folate‐dependent enzyme in the de novo purine synthesis pathway, GART facilitates nucleotide production essential for DNA replication and is frequently overexpressed in aggressive malignancies, including hepatocellular carcinoma, glioma, and colorectal cancer." (PMID 40353332, 2025). "We also knocked down GART and PAICS, 2 key enzymes for de novo purine synthesis, in colorectal cancer cells." (PMID 37252797, 2023).
Down syndrome (5 papers, 2020 to 2025). "The human GART gene is located on Hsa21 and is therefore present in three copies in Down syndrome (DS, Trisomy 21), the most common genetic cause of intellectual disability in humans." (PMID 34283828, 2021). "These exons corresponded to 7 genes, 3 of which have been previously associated with Down syndrome: GART, DNMT3L and AIRE." (PMID 33081811, 2020). "From the hippocampus brain region of Down Syndrome (DS) patients, up-regulation of lncRNAs RMST and GART were observed, and miR-548b-5p/miR-548ad-5p/miR-144-3p were found to be pivotal in regulating the target gene GART expression." (PMID 40251826, 2025). "Our results indicate that GART null cells have a large number of differentially expressed genes (DEG) and may have an important role in embryogenesis, neural development, and perhaps special relevance to Alzheimer’s disease (AD) and Down syndrome (DS)." (PMID 34283828, 2021).
breast carcinoma (3 papers, 2021 to 2023). "However, obesity (a variable linked to high cholesterol levels) is associated with a higher expression of G6PD and GART enzymes, as detected in the basal-like breast tumours of overweight/obese versus lean breast cancer patients." (PMID 34073320, 2021). "The findings presented in this study have identified GART as a new metabolic target that can be used to hinder the growth of breast cancer cells, alongside other targets such as FASN, acid ceramidase, and DHFR." (PMID 37143728, 2023). "GGPS1, FDPS, and GART are upregulated in multiple cancers in addition to breast cancer (also TNBC), including hard-to-treat cancers such as esophageal, pancreatic, lung, and oral cancers and glioblastoma." (PMID 33670680, 2021). "The significance of the overexpression of GGPS1, FDPS, and GART in the pathophysiology of breast cancer is also evident by the fitness dependency of breast cancer cells on these genes." (PMID 33670680, 2021). "Analysis of GART expression in breast tumors revealed that this protein could serve as a promising pharmacological target in ERα-positive breast cancer cells, as patients with low GART mRNA levels have a higher chance of survival." (PMID 37143728, 2023). "The overexpression of GGPS1, FDPS, and GART in breast cancer was also associated with a highly significant overall reduction in the survival of patients with breast cancer compared with that of patients without overexpression of these cellular molecules." (PMID 33670680, 2021). "The levels of GGPS1, FDPS, and GART were significantly elevated in breast tumors as compared to matching adjacent normal tissues, breast cancer cell lines, breast cancer subtypes, and triple negative breast cancer (TNBC) compared with the normal adjacent tissue or non-TNBC tumors." (PMID 33670680, 2021). "Interestingly, our in vitro finding with exogenous cholesterol contradicts the data for the expression of G6PD and GART in the basal-like breast tumours of overweight/obese breast cancer patients." (PMID 34073320, 2021). "However, the expression of G6PD and GART, enzymes associated with the PPP and the OCM pathway (respectively), shows a significant increase in overweight/obese breast cancer patients compared to the lean patients." (PMID 34073320, 2021). "Inhibition of GART by siRNA-mediated depletion or lometrexol (LMX) inhibitor preferentially reduced cell proliferation and induced ERα degradation in ERα-positive IDC cell lines belonging to the LumA clinical surrogate class of breast cancer." (PMID 37143728, 2023). "However, in LumB tumors, women with high GART mRNA levels had higher survival rates than those with low GART mRNA expression, indicating that GART is not a suitable target for this type of breast cancer." (PMID 37143728, 2023).
breast tumors (3 papers, 2021 to 2023). "The overexpression of GGPS1, FDPS, and GART mRNAs and their respective proteins was observed in breast tumors, along with the coexpression of GGPS1, FDPS, and GART proteins in several of the same breast tumors (presented as empty blocks)." (PMID 33670680, 2021). "Because these data suggest that GART expression could have a role in ERα-positive BC progression, we next evaluated its mRNA expression in breast tumors versus normal breast epithelium." (PMID 37143728, 2023). "Among these cell fitness molecules, we observed a widespread mRNA overexpression and copy number amplification of Geranylgeranyl pyrophosphate synthase (GGPS1), Farnesyl diphosphate synthase (FDPS), and GART (also known as glycinamide ribonucleotide formyl transferase—(GARFT) in breast tumors." (PMID 33670680, 2021). "Tissue arrays confirmed that ERα-positive IDCs have higher GART protein levels than ERα-negative IDCs, and metabolomic analyses revealed that glutamine is more abundant in ERα-positive IDC cell lines and breast tumors than in ERα-negative ones." (PMID 37143728, 2023).
glioma (3 papers, 2021 to 2025). A benign or malignant brain and spinal cord tumor that arises from glial cells (astrocytes, oligodendrocytes, ependymal cells). "We also observed that the overexpression of HMGCS1, GGPS1, FDPS, and GART in breast, ovarian, endometrial, pancreatic, and CNS cancers correlated well with a reduction in the overall survival of patients when compared with that of patients without overexpression of these genes." (PMID 33670680, 2021).
lung cancer (3 papers, 2019 to 2025). A malignant neoplasm involving the lung. "Especially, three anti-lung cancer drugs target genes (DHFR, GART and ALK) also presented in the DEGs." (PMID 30642283, 2019). "Three DEGs (DHFR, GART and ALK) also played roles as anti-lung cancer drugs target genes." (PMID 30642283, 2019).
hepatocellular carcinoma (2 papers, 2022 to 2025). A malignant tumor that arises from hepatocytes. "High expression of GART in hepatocellular carcinoma (HCC) is associated with poor prognosis and promotes cancer cell proliferation." (PMID 35565469, 2022).
leukemia (2 papers, 2010 to 2021). A malignant (clonal) hematologic disorder, involving hematopoietic stem cells and characterized by the presence of primitive or atypical myeloid or lymphoid cells in the bone marrow and the blood. "Phosphorylation of Tyr348 in GART was also reported in a human leukemia-derived T-cell line following stimulation with IL-2 or IL-15." (PMID 34283052, 2021). "The application on a dataset of leukemia patients identifies eQTLs in the regions of the GART, PCP4, DSCAM, and RIPK4 genes that regulate ADAMTS1, a known leukemia correlate." (PMID 21044360, 2010).
oral cancer (2 papers, 2021). "We investigated the direct association between ITK and GART, as GART is endogenously expressed in oral cancer cell lines and HEK 293 cells." (PMID 34283052, 2021). "It was suggested that increases in PRPP and IMP in ITK-expressing oral cancer cells are due to the accelerated tyrosine phosphorylation of GART by ITK and activation of the de novo purine biosynthesis pathway." (PMID 34283052, 2021). "In this study, significant increases (51- to 121-fold) in levels of tyrosine phosphorylation of GART were observed in ITK-expressing oral cancer cell lines." (PMID 34283052, 2021). "Furthermore, after confirming the interaction between GART and ITK with HEK 293 cells, a metabolomic analysis was performed in this study using oral cancer cells." (PMID 34283052, 2021). "Increases in GART and activity of the de novo purine biosynthesis pathway, which is a GART metabolic pathway, were confirmed in the ITK-expressing oral cancer cells but not in mock control cells." (PMID 34283052, 2021).
prostate carcinoma (2 papers, 2021 to 2022). A carcinoma that arises from epithelial cells of the prostate gland. "No studies in prostate cancer have investigated the roles or the expressions of the T-complex protein 1 subunit epsilon, encoded by the CCT5 gene, or the trifunctional purine biosynthetic protein adenosine-3, encoded by the GART gene." (PMID 35562881, 2022). "We found that the levels of GGPS1, FDPS, and GART were not upregulated in prostate cancer." (PMID 33670680, 2021). "Similarly, the overexpression of GGPS1, GART, and HMGCS1 reduced the overall survival duration in patients with glioblastoma, ovarian cancer, and endometrial cancer but not in those with prostate cancer." (PMID 33670680, 2021).
COVID-19 (1 paper, 2022). A disease caused by infection with severe acute respiratory syndrome coronavirus 2. "To test for a role for GART in adaptive immune responses associated with susceptibility to severe COVID-19, we used the GART inhibitory drug lometrexol in an in vitro human tonsillar organoid model of T cell-dependent germinal center B cell differentiation." (PMID 35659055, 2022).
folate deficiency (1 paper, 2020). A nutritional condition produced by a deficiency of FOLIC ACID in the diet. "The modeled folate deficiency resulted in a block of purine biosynthesis, because two steps of the purine biosynthetic pathway (catalyzed by the GART and ATIC enzymes) require a folate derivative as a cofactor." (PMID 32384607, 2020). "The GART- and ATIC-encoded enzymes or reactions were also removed from the set of reactions consuming folate which were used in the folate deficiency model." (PMID 32384607, 2020).
hyperuricemia (1 paper, 2024). An abnormally high level of uric acid. "Three genes (GARS, AIRS, and GART) involved in the de novo purine biosynthesis pathway have been mapped to chromosome 21 and excessive purine synthesis gives rise to hyperuricemia, increased plasma adenosine levels, and increased adenosine deaminase activity." (PMID 38960035, 2024).
invasive ductal carcinomas (1 paper, 2023). "ERα-expressing luminal A invasive ductal carcinomas (IDCs) are sensitive to GART inhibition and GART expression is increased in receptor-positive IDCs of high grade and stage and plays a role in the development of ET resistance." (PMID 37143728, 2023).
kidney cancer (1 paper, 2021). Primary or metastatic malignant neoplasm involving the kidney. "Antifolates such as pemetrexed, which are approved for ovarian and kidney cancers, target GART, dihydrofolate reductase, and thymidylate synthase." (PMID 33670680, 2021). "For example, phosphoribosylglycinamide formyl transferase (GART) is an excellent fitness gene in ovarian cancer, for which pemetrexed targeting GART was approved; however, GART is not a fitness gene for lung and kidney cancers." (PMID 33670680, 2021).
lymph node metastasis (1 paper, 2023). "In addition, GART expression was significantly correlated with pathological grade, lymph node metastasis, distant metastasis and survival status, but not with age, gender and tumor site." (PMID 37439412, 2023).
pancreatic cancers (1 paper, 2021). "Additionally, the overexpression of GGPS1, FDPS, GART, and 3-hydroxy-3-methylglutaryl-CoA synthase 1 (HMGCS1) was also associated with a highly significant overall reduction in the survival duration of patients with esophageal and pancreatic cancers." (PMID 33670680, 2021).
sarcoma (1 paper, 2019). A usually aggressive malignant neoplasm of the soft tissue or bone. "Screening the DCGs across 12 cancer types (bladder, breast, colon, esophagus, kidney, liver, lung, skin, ovary, prostate, sarcoma, and thyroid cancers), suggested that these genes could be speculated as metastatic-related genes as DCGs-shared GART and SLC7A5 with 12 tumor types." (PMID 29843204, 2019).
Sepsis (1 paper, 2025). Sepsis is defined as life-threatening organ dysfunction caused by a dysregulated host response to infection. "Integrating WGCNA with three machine learning algorithms, we identified six diagnostic genes—PGM3, GDF15, GART, GFOD2, E2F2, and ATP1B2—associated with sepsis-induced ALI, which were validated in clinical samples by Western blotting." (PMID 41142807, 2025).
cancer (17 papers, 1996 to 2025). A tumor composed of atypical neoplastic, often pleomorphic cells that invade other tissues. "Elevated expression of GART, which is associated with chemosensitivity to multiple drugs, has been used as a target for anti-cancer drugs." (PMID 34818353, 2021). "VGLL3 has been found to modulate glutamine metabolism through regulating the expression of glycinamide ribonucleotide formyltransferase (GART), which encodes a trifunctional enzyme that catalyzes de novo purine synthesis from glutamine in cancer cells." (PMID 38726338, 2024). "ITK is associated with poor clinical outcome in TSCC, and data suggest that ITK enhances the proliferation of cancer cells in the malignant phenotype via activation of de novo purine biosynthesis through phosphorylation of GART." (PMID 34283052, 2021). "Although direct studies on GART’s role in CC are limited, its involvement in nucleotide biosynthesis and its overexpression in other cancers suggest it may contribute to CC progression." (PMID 40599331, 2025). "In this cluster, ADAMTS1 and GART are known cancer biomarkers in ALL." (PMID 21044360, 2010). "Nevertheless, this is the first report demonstrating that ITK is associated with poor clinical outcome in TSCC and that ITK might be involved in enhancing the proliferation of cancer cells in the malignant phenotype via activation of de novo purine biosynthesis through phosphorylation of GART." (PMID 34283052, 2021). "The inhibitor of GART has been reported exerting a cytotoxic and a cytostatic effect on HCT116, MCF7, and A549 cancer cells." (PMID 33281602, 2020). "The DCGs, including GART, TGFB1, ITGA2, SLC16A5, SOX9, and MMP7, were investigated across 12 cancer types." (PMID 29843204, 2019). "In sum, CXCL3, SLC7A5, SLC26A2, GART, and CCDC68 genes were differentially expressed in three or more cancer types." (PMID 29843204, 2019). "In addition, phosphoproteomic and metabolomic analyses were performed to investigate the mechanism of cancer cell proliferation via ITK and the de novo purine biosynthesis pathway via GART phosphorylation." (PMID 34283052, 2021).
tumor (16 papers, 1996 to 2025). "Lomotrexol and AG2034 are GART inhibitors that reduce tumor growth but cause high toxicity." (PMID 32218208, 2020). "In this study, CRC cell lines, mouse models and human tumor tissue were all used to reveal a novel role of GART in CRC, especially in CD133+ CRC stem cells." (PMID 37439412, 2023). "Pemetrexed (PEM), a compound targeting GART, combined with other chemotherapy drugs greatly suppresses tumor growth both in a PDX model and in CRC patients." (PMID 37439412, 2023). "By contrast, GART‐OE HCT‐116 cells caused tumor formation in all 6 nude mice, indicating that GART strengthened the tumor formation capacity in vivo." (PMID 37439412, 2023). "Morphological observations and H&E staining demonstrated that an elevated level of GART led to a significant promotion of tumor metastasis to the liver, whereas treatment with PEM led to a clear reduction in hepatic metastasis." (PMID 37439412, 2023). "Importantly, pharmacological inhibition of GART using LMX not only induces NB differentiation but also significantly attenuates tumor cell proliferation, offering a compelling dual‐targeting approach for high‐risk NB treatment." (PMID 40353332, 2025). "Moreover, the analyses of IHC and H&E staining revealed that the expression levels of GART were higher at the colorectal site and in the tumor tissues in AAV9‐GART‐OE mice compared with the AAV9‐EV mice." (PMID 37439412, 2023). "Therefore, women with LumA tumors had significantly prolonged relapse-free survival rates if the tumor had low GART mRNA levels." (PMID 37143728, 2023). "Interestingly, GART mRNA expression is lower in ERα-positive tumors than in ERα-negative ones, but higher in IDCs than in other histological tumor types." (PMID 37143728, 2023). "Interestingly, GART mRNA expression is increased both in grade 3 tumors with respect to grade 0-2 neoplasms and in BCs classified as stage III-IV with respect to stage 0-II tumors." (PMID 37143728, 2023). "However, it remained unclear whether GART could promote the malignant progression of CRC via modulating tumor stemness." (PMID 37439412, 2023). "The roles of GART were assessed by CCK-8, colony formation, Wound healing assays, and xenograft tumor model." (PMID 40201340, 2025). "Lometrexol, an inhibitor of the purine biosynthesis enzyme phosphoribosylglycinamide formyltransferase (GART), can induce differentiation in MNA-NB and inhibit tumor progression." (PMID 41244073, 2025). "Translationally, pemetrexed, a selective GART inhibitor, combined with CRC chemotherapy drugs significantly suppresses tumor growth and prolongs patient survival." (PMID 37439412, 2023). "WB analysis confirmed that the levels of both the GART and RUVBL1 proteins were elevated in both GART‐OE CRC cell lines and the AOM/DSS‐induced tumor tissues." (PMID 37439412, 2023). "GART also enhances the stability of RuvB‐like AAA ATPase 1 (RUVBL1) through methylating its K7 site, which consequently aberrantly activates the Wnt/β‐catenin signaling pathway to induce tumor stemness." (PMID 37439412, 2023). "Among them, ACAA1, GART, PDE9A, RPL3, TUBA1A, and TUBG1 gene products interact with several proteins known to be involved in the PRAD pathway and particularly important for apoptosis inhibition and tumor growth." (PMID 33712625, 2021). "Additionally, targeting GART, a molecule that regulates the initial substrate in the metabolic chain involving glutamine, induced ERα degradation and prevented tumor cell proliferation, without affecting the survival of non-transformed breast cells." (PMID 37143728, 2023).
GART also shares sentences with these, for which no sentence is quoted: non-small cell lung carcinoma (2 papers); chronic obstructive pulmonary disease (1); Crohn disease (1); developmental delay (1); diabetes (1); endometrial cancer (1); glioblastoma (1); inflammatory skin disorders (1); liver cancer (1); nasopharyngeal carcinoma (1); Obesity (1); osteosarcoma (1); ovarian carcinoma (1); psychiatric disorder (1); thyroid cancer (1); triple-negative breast carcinoma (1).